FASN (fatty acid synthase)
Diseases named in the same sentence as FASN in open-access papers (continued):
Sharing a sentence is not in itself a finding about the gene and the disease.
steatosis (continued). "Here, our results showed that both FASN and ACC protein expression was upregulated upon CAV1 knockdown but downregulated upon CAV1 overexpression in FFA-induced hepatocyte steatosis." (PMID 28570612, 2017). "Improved Lipid Metabolism: The upregulation of peroxisome proliferator-activated receptor alpha (PPARα) and lipoprotein lipase (LPL) expression enhances fatty acid oxidation and lipid clearance, while reduced fatty acid synthase (FAS) expression decreases lipogenesis and steatosis." (PMID 40136563, 2025). "The most upregulated genes associated with steatosis in the macaque alcohol liver disease model (PPARGC1A, IGFBP1, and FASN) were not altered by acute SIV infection." (PMID 38400071, 2024). "Therefore, levels of ACC, FASN and GCK were detected to explore the mechanism of 12-tridecenoic acid on steatosis." (PMID 39246653, 2024). "Human livers have significantly higher expression of FASN in steatosis without significant inflammation as compared to control and NASH livers, suggesting that FASN expression is determined by the severity of disease." (PMID 38514705, 2024). "Here we demonstrated that FASn and CD36 are the direct target genes of AP1, and Hcy activates it to induce their expressions, concurrently stimulating de novo FFA synthesis and uptake to promote hepatic lipid deposition and steatosis." (PMID 39117631, 2024). "Furthermore, we measured increased protein levels of SREBP1, FASN, and ACC upon Trim21 silencing, consistent with the observed enhanced steatosis." (PMID 37937648, 2023). "The first is that AAA-1 promote hepatocyte steatosis in vitro and in vivo, most likely by increasing lipogenesis due to the selective upregulation of SREBP-1 and the transient activation of two key enzymes involved in triglyceride synthesis (FASN and GPAT-1)." (PMID 37798764, 2023). "Finally, inhibition of fatty acid synthase (FAS), which converts acetyl-CoA and malonyl-CoA to palmitate, was also effective in both systems but with stronger effects in the genetic steatosis models." (PMID 36823355, 2023). "Unlike in ZFD-fed mice, we found that hepatic FASN ablation ameliorated steatosis in ob/ob mice and, to a lesser extent, in Mc4r-KO mice." (PMID 37681411, 2023). "Furthermore, the treatment significantly decreased the gene expression of FASN and SREBP1, which were upregulated in steatosis." (PMID 36135761, 2022). "Furthermore, CBD improved alcohol-induced hepatic metabolic dysregulation and steatosis by restoring changes in hepatic expression of ACC-1, FASN, PPARα, MCAD, ADIPOR-1, and mCPT-1." (PMID 35644678, 2022). "Moreover, there was obvious steatosis in the livers of male and female PME fetuses and the mRNA levels of SREBP-1, FASN, and ACC in the liver were significantly increased." (PMID 36499404, 2022). "Apart from rate-limiting enzymes like ACC1 and FASN, several fatty acid synthesis/lipolysis genes are regulated by peroxisome proliferator-activated receptor γ (PPARγ) in liver, and hepatocyte-specific PPARγ KO mice are protected from HFD-induced steatosis." (PMID 35428314, 2022). "Furthermore, CBD improved alcohol-induced hepatic metabolic dysregulation and steatosis by restoring changes in hepatic mRNA or protein expression of ACC-1, FASN, PPARα, MCAD, ADIPOR-1, and mCPT-1." (PMID 28935932, 2017). "Notably, SREBP1 and FASN did not change significantly in the 3D and mouse steatosis models, whereas PGC1A/CPT1A increased in both, consistent with an early metabolic response favoring fatty acid oxidation over robust repression of de novo lipogenesis." (PMID 41035773, 2025). "Notably, downstream of ACACA, the gene expression of Fatty Acid Synthase (FASN) corroborated this observation, demonstrating a significant reduction in lipogenesis in our steatosis model, and a significant elevation in lipogenesis under both nSMase and aSMase inhibition." (PMID 38474427, 2024).
steatosis (continued). "We found that 13-HODE-induced steatosis; moreover, the increased levels of cleaved SREBP1 and FASN were not affected by ΔCAT overexpression in hepatocytes." (PMID 38071367, 2023). "In our experiments, LPS alone did not affect the levels of ACACA, ACACB nor FASN in HepG2 cells, indicating that it does not induce DNL-mediated steatosis in HCC cell model either." (PMID 32284043, 2020). "Notably, the absence of significant SREBP1, FASN, and GLUT2 changes in both the 3D steatosis and the mouse steatosis models indicates cross-model concordance." (PMID 41035773, 2025).
melanoma (64 papers, 2013 to 2026). A malignant, usually aggressive tumor composed of atypical, neoplastic melanocytes. "FASN mutations have been identified as potential biomarkers for predicting the response to ICIs in melanoma patients." (PMID 40376583, 2025). "For example, overexpression of fatty acid synthase (FASN) has been implicated in melanoma progression, contributing to tumor growth and metastasis through its role in producing lipids that promote cell membrane synthesis and signaling molecules." (PMID 40376583, 2025). "Overexpression of FASN has been strongly associated with poor prognosis in melanoma patients, as elevated lipid synthesis fuels tumor cell proliferation, survival, and immune evasion." (PMID 40376583, 2025). "We found that FASN expression is consistently increased upon the onset of therapy resistance in clinical melanoma samples, in cell lines and in Mel006 PDX and is associated with decreased lipid poly-unsaturation." (PMID 37072838, 2023). "As mentioned, we noticed a lower level of mRNA of SC4MOL (implicated in cholesterol biosynthesis), FADS1, and FASN in adipocytes cocultured with melanoma cells." (PMID 37481560, 2023). "Based on the results from the CIBERSORT algorithm, we observed a significantly enhanced infiltration of naive B cells and a decreased infiltration of T regulatory cells in FASN mutated melanoma patients (both p < 0.05)." (PMID 36428733, 2022). "To further understand the possible immunological mechanisms behind FASN mutations in melanoma, we performed a multiangle immunology and pathway analysis." (PMID 36428733, 2022). "We also explored the association between FASN mutations and FASN expression in melanoma and NSCLC patients under the TCGA cohort to elucidate how FASN mutation alters its transcriptional expression." (PMID 36428733, 2022). "FASN mutated melanoma patients exhibited a preferable immunotherapeutic survival than the rest of the patients (p = 0.002)." (PMID 36428733, 2022). "In melanoma patients, FASN mutations were observed to associate with a preferable immunotherapeutic prognosis and response rate (both p < 0.01)." (PMID 36428733, 2022). "We observed that melanoma patients with FASN mutations exhibited a significantly decreased FASN expression (Wilcoxon rank-sum test, p = 0.006), which is consistent with the evidence that patients with low FASN expression responded better to ICI treatments." (PMID 36428733, 2022). "Consistently, in the TCGA melanoma cohort, FASN mutated patients exhibited both increased TMB and NB (both p < 0.001)." (PMID 36428733, 2022). "Further to its role in proliferation, FASN has also been linked to melanoma metastasis, whereby FASN expression correlates with poor prognosis in cutaneous melanoma patients, and inhibition of FASN reduces incidence of metastasis in preclinical in vivo models." (PMID 34830962, 2021). "In this setting, resistance to BRAFi in BRAF-mutant melanoma was associated with decreased FASN expression." (PMID 34068792, 2021). "The negative correlation of FASN levels with BRAFi IC50 values supported the downregulation of FASN expression associated with resistance to BRAFi, pointing to a role for FASN regulation in the effectiveness of BRAFi therapy in melanoma." (PMID 34068792, 2021). "Further to FASN, multiple genes associated with fatty acid metabolism including lipogenesis and fatty acid oxidation are upregulated in melanomas relative to benign nevi." (PMID 32549336, 2020). "Additionally, CAMOIP data analysis revealed that FASN mutations had a better prognosis than wild-type immunotherapy in patients with melanoma." (PMID 36555243, 2022). "However, cycloheximide chase experiment confirms that leptin and resistin cause the stabilization of FASN and Cav-1 protein levels respectively in melanoma cells." (PMID 29568521, 2018).
melanoma (continued). "Considering our previous study on HFD mice, normalized serum levels of these adipokines, via reduced adiposity, could be associated with a reduction in FASN and Cav-1 protein levels and decrease in Akt activation, leading to reduced progression of melanoma in the experimental HFD mice." (PMID 29568521, 2018). "As for the intensity of FASN, a strong intensity like that of control tissue (sebaceous gland or adipose tissue) was detected in a minority of metastatic (36% of primary melanomas and 28% of metastases) and non‐metastatic melanomas (14.2%)." (PMID 40867038, 2025). "Melanoma cells exhibit significant alterations in several lipid metabolic pathways, including FASN, β-oxidation, and cholesterol synthesis." (PMID 40376583, 2025). "Given the significant role of FASN in melanoma, it represents a promising target for combination therapies aimed at improving immunotherapy efficacy." (PMID 40376583, 2025). "For example, inhibiting FASN has been shown to reduce melanoma cell viability, sensitize tumors to ICIs, and slow tumor progression." (PMID 40376583, 2025). "One of the most well-studied features of melanoma metabolism is the increased activity of FASN, which catalyzes de novo fatty acid synthesis." (PMID 40376583, 2025). "Curiously, FASN inhibition can activate the intrinsic apoptosis pathway by mitochondrial involvement in melanoma cells." (PMID 40867038, 2025). "Metastatic and non‐metastatic melanomas showed a marked increase in FASN expression compared to cutaneous nevi." (PMID 40867038, 2025). "B-Raf inhibitor PLX4032-resistant LM16R melanoma cells exhibit reduced FASN levels compared to their sensitive counterparts, notably in LM16 cells." (PMID 38921444, 2024). "Various alterations in fatty acid metabolism are present in melanoma cells, in particular, the upregulation of the expression of fatty acid synthase (FAS) has been evidenced in human melanoma." (PMID 38541630, 2024). "In melanoma cells, Cav-1 interacts with FASN, and elevated levels of both Cav-1 and FASN, along with phosphorylated Akt, promote cell proliferation." (PMID 38921444, 2024). "In malignant melanomas, over-expression of metabolic genes such as fatty acid synthase (FASN) and acetyl-coA carboxylase (ACC) can be found." (PMID 38928466, 2024). "As an example, simultaneous treatment of melanoma cell lines with FASN and DHCR24 inhibitors (PLX4032 and U1866A) increased number of apoptotic cells." (PMID 38672427, 2024). "Based on these reports, FASN is widely recognized as a promising therapeutic target for melanoma and cutaneous squamous cell carcinoma." (PMID 38921444, 2024). "The treatment of orlistat targeting FASN in melanoma LM16R cells leads to the upregulation of DHCR24, activating compensatory pathways that support drug-resistant growth." (PMID 38921444, 2024). "Using gene expression analysis and mass spectrometry-based lipidomics of BRAF-mutant melanoma cell lines, melanoma PDX and clinical data sets, we explored the association of FASN expression with membrane lipid poly-unsaturation and therapy-resistance." (PMID 37072838, 2023). "Taking BRAF-mutant melanoma as paradigm, we demonstrate that FASN expression is consistently increased upon onset of therapy resistance and is associated with decreased lipid poly-unsaturation." (PMID 37072838, 2023). "For example, FA16:0, a fatty acid synthesized by FASN, promotes tumor metastasis in human oral cancer and human melanoma." (PMID 37712874, 2023). "It was revealed that leptin not only enhances melanoma cell proliferation, but also decreases dacarbazine treatment effectiveness by means of the up-regulation of fatty acid synthase (FASN) and heat shock protein 90 (Hsp90)." (PMID 37298551, 2023). "Most of the enzymes associated with fatty acid synthesis (e.g., FASN, SCD, ACC, ACLY), and receptors related to lipid uptake (e.g., FAT/CD36, FATPs, and FABPpm) are upregulated in several cancers, including melanoma." (PMID 35406721, 2022).
melanoma (continued). "The overexpression of FASN is significantly detected in many types of tumors, including lung, stomach, prostate, ovary, bladder, oral cavity, and melanoma." (PMID 35350838, 2022). "In both anti-PD-L1 immunotherapy of BLCA and anti-CTLA-4 immunotherapy of melanoma, high expression of FASN predicted a poor prognosis." (PMID 36555243, 2022). "Ultimately, we identified a pattern in which patients with high FASN expression tended to be more responsive to immunotherapy, which was observed in the melanoma immunotherapeutic cohort among the four cohorts evaluated." (PMID 36555243, 2022). "Cerulenin, a fatty acid synthase inhibitor, can retard the growth of melanoma cells and activates caspase-dependent apoptosis." (PMID 36685905, 2022). "In BRAF-inhibitor resistant melanoma cells, we explored the role of FASN, an enzyme involved in lipogenesis overexpressed in metastatic melanoma." (PMID 34068792, 2021). "Here, we found that molecular targeting of FASN in melanoma cells resistant to the BRAF inhibitor PLX4032 increased the sensitivity to the drug." (PMID 34068792, 2021). "Based on this background, the rationale of the study was designed to explore the possible role of FASN in relation to BRAFi resistance in melanoma cells, in order to improve the efficacy of BRAFi for combination studies." (PMID 34068792, 2021). "In conclusion, FASN plays a role in BRAF-mutated melanoma progression, thereby creating novel therapeutic opportunities for the treatment of melanoma." (PMID 34068792, 2021). "Cav-1, stabilized by FASN by palmitoylation, is involved in drug resistance and therefore constitutes a tumor-promoting factor in melanoma." (PMID 33430277, 2021). "FASN inhibition by orlistat has been reported to reduce proliferation and lymph node metastasis and to promote apoptosis in a mouse model of spontaneous melanoma metastasis." (PMID 34068792, 2021). "The gene expression and drug combination results reported here, together with the availability of well-tolerated FASN inhibitors, support the interest of clinical testing of FASN-targeting as a strategy to improve BRAFi efficacy in melanoma." (PMID 34068792, 2021). "It was shown that both leptin and resistin, two hormones released by adipocytes, stimulate melanoma cell proliferation in vitro by regulating FASN as well as the AKT-based signal transduction pathway." (PMID 33430277, 2021). "FASN expression correlates with poor prognosis in cutaneous melanoma, and inhibition of FASN reduces proliferation of B16–F10 melanoma cells in vitro and reduces incidence of metastasis in vivo." (PMID 32549336, 2020). "In the context of melanoma, and indeed many other tumor types, SREBPC1c, and consequently FASN expression, is constitutively driven by the mitogen-activated protein kinase (MAPK) and phosphoinositide-3-kinase (PI3K) signaling pathways." (PMID 32549336, 2020). "Consistently, FA synthase (FASN) inhibition with orlistat reduces lymphangiogenesis, leading to a decrease in the number of LN metastases in a melanoma model." (PMID 33203856, 2020). "The specific inhibition of FASN activity with the anti-obesity drug Orlistat was reported to reduce the occurrence and number of lung metastases in a murine model of melanoma." (PMID 33121001, 2020). "Upon leptin and resistin treatment using A375 melanoma cell line, fatty acid synthase (FASN) and caveolin 1 (Cav-1), respectively, were found increased." (PMID 32509589, 2020). "Melanoma cells show high fatty acid synthase and acetyl-CoA carboxylase (key enzymes in the de novo pathway of fatty acid synthesis) compared to benign nevi, suggesting an increase in de novo fatty acid synthesis in melanoma patients." (PMID 31344914, 2019). "Western blot data demonstrated that IT markedly suppressed the expression of FASN in A375S and A2058 melanoma cells." (PMID 27323414, 2016).